MIR4295 (microRNA 4295)
Synonyms: hsa-mir-4295
Gene: MicroRNA gene on chromosome 10 (112,634,170 to 112,634,254, forward strand). Ensembl gene ENSG00000264763.
Homologues: Orthologues: chimpanzee MIR4295 (100% identical).